HNRNPK (heterogeneous nuclear ribonucleoprotein K)
Diseases named in the same sentence as HNRNPK in open-access papers (continued):
Sharing a sentence is not in itself a finding about the gene and the disease.
lung carcinoma (24 papers, 2014 to 2024). "Based on the single-cell and bulk transcriptome of lung cancer, we identified 9 cancer hallmark-related pathways that were potentially activated by HNRNPK." (PMID 36681772, 2023). "All these results suggested that HNRNPK functions as an oncogene and play important roles in lung cancer." (PMID 36681772, 2023). "We also found that HNRNPK exhibited significantly higher expression in lung cancer cells than other immune cells." (PMID 36681772, 2023). "We demonstrated that HNRNPK functions as an oncogene in lung cancer by binding MYC mRNAs to promote the cancer development and progression." (PMID 36681772, 2023). "To further confirm the function of HNRNPK in A549 cells in vivo, we constructed a mouse model of human lung cancer xenograft." (PMID 36681772, 2023). "For example, there were three motifs (UCCCCCAA_1029, ACCCCCCCCCUA_s61 and CCCCCCC_1026) of HNRNPK were significantly enriched in lung cancer." (PMID 36681772, 2023). "We first constructed a shRNA and overexpression HNRNPK lentiviral vectors to construct knockdown and overexpression HNRNPK cell models separately to explore the biological function of HNRNPK in human lung cancer cell line A549 cells." (PMID 36681772, 2023). "To uncover the molecular mechanism of BC‐mediated EGFR‐TKI resistance in lung cancer, we screened and identified nucleolin and hnRNPK that interact with BC." (PMID 36650118, 2023). "In particular, we prioritized the HNRNPK in lung cancer and validated its functions in cell lines and animal models." (PMID 36681772, 2023). "All these results suggested that HNRNPK plays important functions in lung cancer by perturbing the MYC signaling pathway." (PMID 36681772, 2023). "Our applications of RBPreg in cancers provided a valuable resource for characterizing RBP regulatory networks, and reveal oncogenic HNRNPK-MYC signaling pathway in lung cancer." (PMID 36681772, 2023). "In summary, we found that hnRNPK knockdown significantly inhibited the proliferation and migration of lung cancer cells." (PMID 35352475, 2022). "Briefly, hnRNPK was knocked down in lung cancer cell lines, and effects of knockdown on the cell proliferation, migration, and cell cycle were assessed using a cell counting kit‐8 (CCK‐8) assay, colony formation assay, transwell assay and flow cytometry." (PMID 35352475, 2022). "Considering high hnRNPK expression in lung cancer tissues, we transfected siRNA with a specific hnRNPK knockdown into the human lung cancer cell lines A549 and H1299." (PMID 35352475, 2022). "Together, these observations suggest that hnRNPK acts as a promoting factor in lung cancer cells by regulating cell cycle." (PMID 35352475, 2022). "Collectively, these results suggest that hnRNPK expression is dynamic and that hnRNPK plays an important role in the development of lung cancer." (PMID 35352475, 2022). "Candidate genes ACTR3, ARPC5, and HNRNPK were highly expressed in almost all types of lung cancer immune cells, while RAB13, PA2G4, and WDR12 were found to be less abundant in the majority of myeloid populations in lung cancer." (PMID 34868230, 2021). "From these results, we confirmed that hnRNPK/LINC00263/miR-147a/CAPN2 regulatory axis is very closely related to the malignant phenotype of lung cancer cells." (PMID 33731671, 2021).
lung carcinoma (continued). "In order to investigate how the interaction influences the metastasis of lung cancer cells, we enhanced hnRNPK overexpression in A549 cells, which enhanced migration of A549 cells after TGF-β1 treatment." (PMID 31492158, 2019). "In this study, the results demonstrated hnRNPK promoted metastasis and microtubule stability of lung cancer cells via interaction with LC1 after TGF-β1 treatment, indicating that MAP 1B-LC1 is required for hnRNP K-mediated EMT induced by TGF-β1." (PMID 31492158, 2019). "These indicated LC1 is crucial for hnRNPK to promote lung cancer cell metastasis under treatment with TGF-β1." (PMID 31492158, 2019). "In order to provide the clinical evidence of the regulation of GSK3β Ser9 phosphorylation by hnRNPK in lung cancer, we have performed the immunohistochemical essays using two commercialized tissue microarrays." (PMID 26972480, 2016). "In this support, interaction of hnRNPK, hnRNPC, hnRNPL and hnRNPA2/B1 with hnRNPD in cervical and lung cancer cells has been reported earlier." (PMID 26318153, 2015). "The current study examined the effects of heterogeneous nuclear ribonucleoprotein K (hnRNP K)-targeted small interfering RNA (siRNA) on the growth and apoptosis of lung cancer cells in vitro." (PMID 24944671, 2014). "Moreover, patients in high stages were with significantly higher expression of HNRNPK in lung cancer (p = 0.0018 for Kruskal–Wallis test)." (PMID 36681772, 2023). "In this study, we revealed the association between HNRNPK and MYC signaling pathway in lung cancer." (PMID 36681772, 2023). "Furthermore, the expression levels of hnRNPK in gefitinib resistant lung cancer cell lines were also elevated according to the GEO database (GSE75309, GSE34228 and GSE38310)." (PMID 36650118, 2023). "Similarly, other studies have revealed that hnRNPK was highly expressed in primary lung cancer tissues and the positive rate of hnRNPK expression was higher in cancer tissue that in normal tissues and inflammatory controls." (PMID 35352475, 2022). "In the present study, we focused on hnRNPK expression in lung cancer and explored the hypothesis that hnRNPK promotes tumor progression." (PMID 35352475, 2022). "hnRNPK was generally high in lung cancer tissues, suggesting its oncogenic role." (PMID 35352475, 2022). "In this study, hnRNPK expression in lung cancer tissues was investigated." (PMID 35352475, 2022). "Finally, the effect of hnRNPK knockdown on tumor growth was verified in vivo using a lung cancer xenograft mouse model." (PMID 35352475, 2022). "Moreover, in our previous studies, we demonstrated that hnRNPK expression is strongly correlated with biological processes such as cell migration and invasion and that it is an important factor for lung cancer metastasis." (PMID 35352475, 2022). "hnRNPK plays a crucial role in the progression of lung cancer, ultimately affecting survival rate." (PMID 35352475, 2022). "Although previous research has revealed some effects of HNRNPK in cancer and normal cells, the exact role of HNRNPK in lung cancers is still unknown and requires further investigation." (PMID 31942561, 2019). "Although our model reveals some mechanisms surrounding the role of HNRNPK in lung cancer metastasis, the mechanism and factors involved in the regulation of HNRNPK expression are still unknown and need to be investigated in the future." (PMID 31942561, 2019). "These imply that hnRNPK may promote lung cancer cells migration via regulating microtubule stability." (PMID 31492158, 2019). "Strikingly, in the same histological section of lung cancer, we were able to simultaneously observe the low hnRNPK expression accompanied with the high level of phospho-GSK3β in a region (the arrows), and the opposite pattern in a neighbouring zone (the stars)." (PMID 26972480, 2016). "Moreover, we investigated the expression of HNRNPK in lung cancer two cohorts from TCGA project." (PMID 36681772, 2023).
lung carcinoma (continued). "It is hypothesized that hnRNPK also plays a role via the similar signaling pathway in lung cancer." (PMID 35352475, 2022). "HnRNPK could therefore be a potential therapeutic target for the treatment of lung cancer." (PMID 35352475, 2022). "Furthermore, hnRNPK is known to interact with linc00460 to promote lung cancer cell metastasis." (PMID 31110205, 2019). "Blockade of HNRNPK function using inhibitors may prevent lung cancer formation." (PMID 31942561, 2019). "Additionally, the expression of HNRNPK in lung cancer cells may help to determine the prognosis of patients." (PMID 31942561, 2019). "Mechanistic investigations further demonstrate that HNRNPK promotes tumorigenesis and progression by directly binding to MYC and perturbed the MYC targets pathway in lung cancer." (PMID 36681772, 2023). "Although emerging studies have revealed the important functions of HNRNPK and MYC in cancer, limited evidence were supported in lung cancer." (PMID 36681772, 2023). "Moreover, HNRNPK has been reported and could promote metastasis in lung cancer." (PMID 34737768, 2021). "Compared to that in WI-38 cells, the expression of HNRNPK and LINC00263 was significantly increased in both lung cancer cells." (PMID 33731671, 2021). "One study reported that LINC00460 interacts with hnRNPK to promote EMT and cell migration in lung cancer cells." (PMID 31429766, 2019). "To assess the clinical significance of hnRNPK, we assessed hnRNPK expression patterns in lung cancer tissues of 94 patients who had not received chemotherapy before surgery." (PMID 35352475, 2022). "Linc00460 binds with and translocates hnRNPK that is located in nucleus to the cytoplasm to participate in special mRNA stability and translation regulation, and promotes cell migration and invasion through inducing EMT in lung cancer formation." (PMID 35505438, 2022). "Linc00460 binds with and translocates hnRNPK that is located in nucleus to the cytoplasm to participate in special mRNA stability and translation regulation, and promotes cell migration and invasion through inducing EMT in lung cancer." (PMID 35505438, 2022). "In this study, we focused on the possible role of hnRNPK-GSK3β interaction in the regulation of the protein stability of c-FLIP, as well as the related functional consequence on the resistance to TRAIL-induced apoptosis of lung cancer cells." (PMID 26972480, 2016). "Furthermore, negative correlation between the level of hnRNPK and the Ser9 phosphorylated GSK3β could be established in both lung cancer and normal tissues." (PMID 26972480, 2016). "In addition, we compared the level of HNRNPK mRNA and LINC00263 in two lung cancer cells with those in non-cancerous WI-38 cells." (PMID 33731671, 2021).
prostate carcinoma (24 papers, 2009 to 2024). A carcinoma that arises from epithelial cells of the prostate gland. "For example, lnc-LBCS directly interacts with hnRNPK and forms a complex with hnRNPK and AR mRNA to inhibit AR translation efficiency and cancer progression in castrated prostate cancer research." (PMID 35571069, 2022). "Reportedly hnRNPK serves as an oncogene in colorectal cancer, nasopharyngeal carcinoma, prostate cancer, melanoma, oral squamous cell carcinoma, and gastric cancer, such that its overexpression is negatively correlated with tumorigenesis and prognosis." (PMID 35352475, 2022). "In colorectal and prostate cancers, HNRNPK in the nucleus enhance the transcriptional activity of MMP2 to facilitate cell invasion." (PMID 36439880, 2022). "In the present study, we noted that HnRNPK emerged as an important player in the carcinogenesis process of prostate cancer." (PMID 34857003, 2021). "On the other hand, cytoplasmic hnRNPK was proposed to down‐regulate AR mRNA translation in prostate cancer." (PMID 33931969, 2021). "For example, LncRNA LBCS suppresses castration resistance and proliferation of prostate cancer by functioning as a scaffold for hnRNPK protein and AR mRNA to inhibit AR translation efficiency." (PMID 33643926, 2021). "In prostate cancer, hnRNPK localisation was previously reported to regulate androgen receptor (AR) activity and prostate cancer prognosis." (PMID 33931969, 2021). "For example, lncRNA LBCS suppressed the castration resistance and proliferation of prostate cancer cells by functioning as a scaffold of hnRNPK protein and AR mRNA to inhibit AR translation efficiency." (PMID 32351538, 2020). "Lnc-LBCS functions as a novel AR translational regulator that suppresses castration resistance of prostate cancer by interacting with hnRNPK." (PMID 31221168, 2019). "Using proteomic analysis of the nuclear matrix (NM), we found that heterogeneous nuclear ribonucleoprotein K (hnRNP K), a member of the hnRNP family with pleiotropic functions, was differentially expressed in prostate cancer (PCa) tissues." (PMID 19401687, 2009). "hnRNPK inhibits the translation of AR mRNA in prostate cancer." (PMID 36735291, 2023). "In addition, caveolin-1 regulates translocation of hnRNPK to lipid rafts on the limiting membrane of MVBs, whereby hnRNPK together with its bound microRNAs are sorted into ILVs/exosomes in PC3 prostate cancer cells." (PMID 36320056, 2022). "We have further provided evidence that Cullin 3 SPOP is a novel upstream E3 ubiquitin ligase complex that governs HnRNPK protein stability and oncogenic functions by promoting the degradation of HnRNPK in polyubiquitination-dependent proteolysis in the prostate cancer setting." (PMID 34857003, 2021). "More importantly, given the critical oncogenic role of HnRNPK and the high frequency of SPOP mutations in prostate cancer, our results provide a molecular rationale for the clinical investigation of novel strategies to combat prostate cancer based on SPOP genetic status." (PMID 34857003, 2021). "Moreover, prostate cancer-associated SPOP mutants fail to interact with and promote the destruction of HnRNPK proteins." (PMID 34857003, 2021). "Collectively, these results indicate that HnRNPK inhibits PrCa cell proliferation in vitro and in vivo via its effects on the cell cycle and may play oncogenic roles in prostate cancer progression." (PMID 34857003, 2021). "However, both the transcriptional regulation and degradation of HnRNPK in prostate cancer remain poorly understood." (PMID 34857003, 2021). "In addition, hnRNPK regulates and directly interacts with the androgen receptor translational apparatus in prostate cancer." (PMID 33806648, 2021). "For example, lncRNA LBCS was shown to suppress castration resistance and proliferation of prostate cancer cells by functioning as a scaffold of hnRNPK (Heterogeneous nuclear ribonucleoprotein K) protein and AR (Androgen receptor) mRNA to inhibit AR translation efficiency." (PMID 32351538, 2020).
prostate carcinoma (continued). "Interestingly, a previous report found that hnRNPK is critical suppressor of AR translation, and the expression of hnRNPK and AR is negatively correlated in prostate cancer." (PMID 31221168, 2019). "To determine if CAVIN1 directly influences hnRNPK localisation or acts by neutralizing non‐caveolar CAV1, we ectopically expressed CAV1 in two cell lines that naturally lack CAV1 and CAVIN1, namely the androgen‐sensitive prostate cancer cell line LNCaP, and human embryonic kidney HEK293 cells." (PMID 33931969, 2021).
hepatocellular carcinoma (20 papers, 2012 to 2025). A malignant tumor that arises from hepatocytes. "ELF3-AS1 has been strongly linked to the prognosis of glioma and hepatocellular carcinoma and has been shown to accelerate gastric cancer progression through binding to hnRNPK." (PMID 40034693, 2025). "Previous studies have reported that the KH3 domain was the site of hnRNPK SUMOylation and that noncoding RNA could regulate the SUMOylation of hnRNPK in hepatocellular carcinoma." (PMID 34452628, 2021).
gastric cancer (17 papers, 2017 to 2025). A primary or metastatic malignant neoplasm involving the stomach. "Compared with negative control group, 917 genes were significantly changed in HNRNPK-silenced gastric cancer cells." (PMID 29262567, 2017). "Our study demonstrated that HNRNPK may play as a tumor suppressor in gastric cancer and could be a potential therapeutic target for GC." (PMID 29262567, 2017). "Here, we demonstrated that circFAM73A binds to HNRNPK, enhances the interaction between HNRNPK and β-catenin and facilitates the stability of β-catenin, thus promoting CSC-like properties in gastric cancer." (PMID 33731207, 2021). "In summary, our study uncovered that NAT10-mediated ac4C modification stabilizes lncRNA XIST, which recruits hnRNPK to facilitate YAP1 nuclear translocation and transcriptional activation, thereby driving VEGFA-dependent vascular abnormalization in gastric cancer." (PMID 40860183, 2025). "circFAM73A promotes HNRNPK recruitment, improves the interaction between β-catenin and HNRNPK, and promotes β-catenin stability, consequently promoting CSC-like characteristics in gastric cancer." (PMID 39170516, 2024). "In summary, it is our novel discovery that low transcript level of HNRNPK correlates with poor prognosis in gastric cancer, especially in early stage and no metastasis patients." (PMID 29262567, 2017). "Thus, we hypothesized that XIST recruits hnRNPK to promote the nuclear translocation of the YAP1 protein and YAP1/TEAD4-mediated VEGFA transcription in gastric cancer cells." (PMID 40860183, 2025).